DHX16 (DEAH-box helicase 16)
Description:
Required for pre-mRNA splicing as a component of the spliceosome. Contributes to pre-mRNA splicing after spliceosome formation and prior to the first transesterification reaction. As a component of the minor spliceosome, involved in the splicing of U12-type introns in pre-mRNAs (Probable). Also plays a role in innate antiviral response by acting as a pattern recognition receptor sensing splicing signals in viral RNA. Mechanistically, TRIM6 promotes the interaction between unanchored 'Lys-48'-polyubiquitin chains and DHX16, leading to DHX16 interaction with RIGI and ssRNA to amplify RIGI-dependent innate antiviral immune responses.
Synonyms: DBP2; DDX16; PRP2; PRPF2; NMOAS; PRO2014; PRP8
Tractability: Small molecule: a structure with a bound ligand is known. PROTAC: ubiquitination databases record sites on it; its protein half-life has been measured.
Gene: Protein-coding gene on chromosome 6 (30,653,119 to 30,673,013, reverse strand). Ensembl gene ENSG00000204560.
Subcellular location: Nucleus; Nucleus, nucleoplasm; Cytoplasm
Subcellular location (Human Protein Atlas): Nucleoplasm
Pathways (Reactome):
Disease: Dengue Virus-Host Interactions
Metabolism of RNA: mRNA Splicing - Major Pathway
Gene Ontology:
Molecular function: molecular adaptor activity; pattern recognition receptor activity; protein binding; RNA binding; ubiquitin binding; helicase activity; RNA helicase activity; ATP binding; ATP hydrolysis activity; ATP-dependent activity, acting on RNA; nucleic acid binding
Biological process: antiviral innate immune response; mRNA splicing, via spliceosome; RNA splicing
Cellular component: cytoplasm; nucleoplasm; nucleus; spliceosomal complex; U12-type catalytic step 2 spliceosome; U2-type catalytic step 1 spliceosome; U2-type precatalytic spliceosome; catalytic step 2 spliceosome; ribonucleoprotein complex
Genetic constraint (gnomAD): Loss-of-function variants: 81 observed, 136.03 expected, observed/expected ratio (o/e) 0.6, 90% interval 0.5 to 0.72. The synonymous counts are far from expectation, so gnomAD's model fits this gene poorly and the ratio says little. Missense variants: 980 observed, 1,419.6 expected, observed/expected ratio (o/e) 0.69, 90% interval 0.65 to 0.73. Synonymous variants: 440 observed, 547.15 expected, observed/expected ratio (o/e) 0.8, 90% interval 0.74 to 0.87.
Homologues: Orthologues: chimpanzee DHX16 (99% identical), macaque DHX16 (99% identical), pig DHX16 (98% identical), rabbit DHX16 (96% identical), rat Dhx16 (96% identical), mouse Dhx16 (96% identical), guinea pig DHX16 (92% identical), dog DHX16 (91% identical), zebrafish dhx16 (74% identical), tropical clawed frog dhx16 (73% identical), Drosophila melanogaster l(2)37Cb (56% identical), Caenorhabditis elegans mog-4 (55% identical). Paralogues in human: DHX8 (43% identical), DHX38 (38% identical), DHX15 (34% identical), DHX35 (30% identical), DHX33 (29% identical), DHX37 (27% identical), DHX40 (25% identical), DHX57 (25% identical), DHX34 (24% identical), DHX29 (23% identical), YTHDC2 (22% identical), DHX9 (22% identical), and 6 more.
Diseases named in the same sentence as DHX16 in open-access papers:
DHX16 is named in the same sentence as 17 diseases in open-access papers, as found by Europe PMC text mining. Sharing a sentence is not in itself a finding about the gene and the disease. The quoted sentences say what the papers report.
lung carcinoma (4 papers, 2017 to 2024). "Among them, 18 genes were essential for cancer cell proliferation, such as NSF for breast cancer, CCND1 for renal cell cancer, DHX16 for lung cancer, CDC27 for ovarian cancer, and CTDP1 for prostate cancer." (PMID 39025880, 2024). "The single nucleotide polymorphism (SNP) of rs115420460 in DHX16 was significantly different in lung cancer samples compared with controls from the TRICL Consortium, and was demonstrated to be associated with lung cancer risk." (PMID 35993327, 2022). "SNPs in DHX16 (rs115420460) and LSM2 (rs114312980, rs115489726, rs115801685, rs114637560, rs115834633) were excluded from further analysis due to their locations within the previously identified lung cancer susceptible region Chr6p21.33 and in high LD with previously reported lung cancer GWAS SNPs." (PMID 28304396, 2017). "MEST, DHX16 and RNPC7 were not only upregulated in highly invasive A549-i8 cells, but also highly expressed in lung cancer." (PMID 34560900, 2021). "With a relatively loose threshold (p < .2), the genes Dhx16, Upf2, Denr, Notch3, Dyrk2, Sec61a1, Hmmr, and Noa1 were reversed in at least three treatment protocols and most of these genes were reported to be related to COPD or lung cancer." (PMID 35993327, 2022).
prostate carcinoma (2 papers, 2023 to 2024). A carcinoma that arises from epithelial cells of the prostate gland. "Notably, the results showed that LSM3 and DHX16 were significantly associated with the fitness of prostate cancer cells, suggesting that these two SFs might be involved in controlling key processes for tumour cell survival and proliferation." (PMID 37559353, 2023). "Through such comprehensive approaches, the roles of LSM3 and DHX16 in prostate cancer progression can be better understood." (PMID 37559353, 2023). "Further molecular biology investigations are suggested to elucidate LSM3 and DHX16's mechanisms in prostate cancer progression." (PMID 37559353, 2023).
retinitis pigmentosa (2 papers, 2025). Retinitis pigmentosa (RP) is an inherited retinal dystrophy leading to progressive loss of the photoreceptors and retinal pigment epithelium and resulting in blindness usually after several decades. "Here, we report a unique case of de novo DHX16 gene mutation presenting with both retinitis pigmentosa and sensorineural deafness." (PMID 41555919, 2025). "We describe a case of a 36-year-old female with neuromuscular disease, sensorineural hearing loss, retinitis pigmentosa, and primary ovarian insufficiency harboring a heterozygous de novo missense pathogenic variant in the DEAH-box helicase 16 (DHX16) gene." (PMID 40141454, 2025).
autoimmune disease (1 paper, 2021). A disorder resulting from loss of function or tissue destruction of an organ or multiple organs, arising from humoral or cellular immune responses of the individual to their own tissue constituents. "DHX16 is linked to several malignant and autoimmune diseases, and its role in innate immunity has been documented." (PMID 34899357, 2021).
leukemia (1 paper, 2019). A malignant (clonal) hematologic disorder, involving hematopoietic stem cells and characterized by the presence of primitive or atypical myeloid or lymphoid cells in the bone marrow and the blood. "In our data, nanosecond pulsed electric field exposure provoked significant increases of DHX15 and DHX16 expression in Jurkat cells, indicating that nanosecond pulsed electric fields treatment may affect the gene expression of leukemia cells." (PMID 31766457, 2019). "To further explore the clinical significance of these hub genes (SUGP1, DHX16, FUS, HNRNPR, DHX15, NAA38, SKIV2L2, and PLRG1), we used a series of online tools to evaluate the clinical expression of these hub genes in leukemia." (PMID 31766457, 2019).
sensorineural deafness (1 paper, 2025). "Here, we present two cases of de novo DHX16 gene mutation resulting in both RP and sensorineural deafness." (PMID 41555919, 2025).
cancer (6 papers, 2021 to 2024). A tumor composed of atypical neoplastic, often pleomorphic cells that invade other tissues. "As for DHX16, it has been suggested to be involved in multiple biological processes, such as innate antiviral immunity and pre‐mRNA splicing, but it has not received attention in the field of cancer." (PMID 37559353, 2023). "Notably, most of the cancer types that showed higher irAE ROR than predicted by the combined PD-L1 protein expression and fPD1 model had higher DHX16 expression abundances, whereas those showing lower than bivariate model-based predicted irAE risk had lower DHX16 expression levels." (PMID 34899357, 2021).
genetic disorders (1 paper, 2025). "The DHX16 gene, which encodes a protein involved in RNA processing, has been implicated in several genetic disorders." (PMID 41555919, 2025). "The DHX16 gene encodes a protein involved in RNA processing and has been associated with several genetic disorders." (PMID 41555919, 2025).
DHX16 also shares sentences with these, for which no sentence is quoted: tumor (2 papers); viral infection (2); adenoma (1); breast carcinoma (1); colorectal adenoma (1); COVID-19 (1); neuromuscular disease (1); ovarian carcinoma (1); renal cell cancer (1).